GSTA2 (glutathione S-transferase alpha 2)
Description:
Catalyzes the conjugation of glutathione to a large variety of electrophilic compounds.
Synonyms: GST2; GSTA2-2; GTA2; GTH2
Tractability: Small molecule: it has a high-quality binding pocket. PROTAC: its protein half-life has been measured; a small molecule that binds it is known.
Target class: Enzyme; Transferase
Gene: Protein-coding gene on chromosome 6 (52,747,975 to 52,763,525, reverse strand). Ensembl gene ENSG00000244067.
Subcellular location: Cytoplasm
Subcellular location (Human Protein Atlas): Cytosol
Pathways (Reactome):
Drug ADME: Azathioprine ADME
Immune System: Gene and protein expression by JAK-STAT signaling after Interleukin-12 stimulation
Metabolism: Glutathione conjugation
Gene Ontology:
Molecular function: protein binding; glutathione transferase activity
Biological process: epithelial cell differentiation; glutathione metabolic process; xenobiotic metabolic process
Cellular component: cytosol; extracellular exosome; cytoplasm
Genetic constraint (gnomAD): Loss-of-function variants: 24 observed, 20.55 expected, observed/expected ratio (o/e) 1.17, 90% interval 0.84 to 1.63. The synonymous counts are far from expectation, so gnomAD's model fits this gene poorly and the ratio says little. Missense variants: 287 observed, 247.33 expected, observed/expected ratio (o/e) 1.16, 90% interval 1.05 to 1.28. Synonymous variants: 115 observed, 83.27 expected, observed/expected ratio (o/e) 1.38, 90% interval 1.19 to 1.61.
Homologues: Orthologues: chimpanzee GSTA2 (99% identical), rat Gsta3l1 (57% identical), zebrafish gstp1.1 (30% identical), tropical clawed frog gstp1 (29% identical), Caenorhabditis elegans gst-3 (27% identical), Caenorhabditis elegans gst-23 (27% identical), Caenorhabditis elegans gst-37 (27% identical), Caenorhabditis elegans gst-29 (26% identical), Caenorhabditis elegans gst-39 (26% identical), Caenorhabditis elegans gst-41 (26% identical), Caenorhabditis elegans W10C8.4 (25% identical), Caenorhabditis elegans gst-10 (25% identical), and 31 more. Paralogues in human: GSTA1 (95% identical), GSTA3 (89% identical), GSTA5 (89% identical), GSTA4 (54% identical), GSTP1 (29% identical), GSTM2 (27% identical), GSTM1 (25% identical), GSTM4 (24% identical), GSTM3 (24% identical), GSTM5 (23% identical), HPGDS (21% identical).
Diseases named in the same sentence as GSTA2 in open-access papers:
GSTA2 is named in the same sentence as 32 diseases in open-access papers, as found by Europe PMC text mining. Sharing a sentence is not in itself a finding about the gene and the disease. The quoted sentences say what the papers report.
hepatocellular carcinoma (4 papers, 2021 to 2024). A malignant tumor that arises from hepatocytes. "GSTA1 and GSTA2 have been previously identified as biomarkers of liver injury (including ethanol injury) and hepatocellular carcinoma respectively." (PMID 38335183, 2024). "Another group also showed that the overexpression of GSTA2 has a protective effect against ROS-induced cell death in hepatocellular carcinoma (HCC) cells." (PMID 36769090, 2023).
cholestasis (2 papers, 2017 to 2024). Impairment of the bile flow caused by obstruction within the liver, or outside the liver in the bile duct system. "In the context of gallstone formation, characterized by cholestasis, our findings reveal a notable downregulation of GSTA2 in the gallstone group, indicating a weakened detoxification capacity of the liver against toxic bile acids." (PMID 38808330, 2024). "After ANIT-induced cholestasis was treated with fenofibrate, the levels of Gsta2, Gsta4, Gstm3, and Gpx2 were significantly decreased (P < 0.01)." (PMID 28855630, 2017). "In our study, the expression levels of Gsta2, Gsta4, Gstm3 and Gpx2 were increased in the ANIT-induced cholestasis." (PMID 28855630, 2017).
colon cancer (2 papers, 2022 to 2025). "Previous studies have found that overexpression of GSTA2 protects colon cancer cells against crosslinking agent-induced DNA damage." (PMID 35936694, 2022). "Gsta2 was found to protect against cell cycle arrest and apoptosis in colon cancer cells." (PMID 40083382, 2025).
Parkinson disease (2 papers, 2020 to 2023). A progressive degenerative disorder of the central nervous system characterized by loss of dopamine producing neurons in the substantia nigra and the presence of Lewy bodies in the substantia nigra and locus coeruleus. "Here, we demonstrated that capsaicin can protect against 6-OHDA-induced Parkinson's disease and reduce the apoptosis rate by regulating Actg1 and Gsta2 in a cell model." (PMID 32537633, 2020). "CCK-8 detection and flow cytometry demonstrated that overexpression of Actg1 and Gsta2 increased apoptosis in the 6-OHDA-induced Parkinson's disease cell model." (PMID 32537633, 2020). "The present study showed that regulation of Actg1 and Gsta2 is the possible mechanism by which capsaicin alleviates apoptosis in a cell model of 6-OHDA-induced Parkinson's disease." (PMID 32537633, 2020). "Here, our experiments demonstrated that overexpression of Actg1 (actin gamma 1) and Gsta2 increased apoptosis in a cell model of 6-OHDA-induced Parkinson's disease." (PMID 32537633, 2020). "The imbalance between Actg1 and Gsta2 may be one of the mechanisms of cell damage in Parkinson's disease (PD)." (PMID 32537633, 2020).
Ureteral obstruction (2 papers, 2016 to 2022). Obstruction of the flow of urine through the ureter. "Gsta2 is a downstream signaling molecule of Nrf2 and also participates in the antioxidant stress effect of Nrf2, which was researched in the mice with surgically induced Unilateral ureteral obstruction (UUO)." (PMID 36157062, 2022).
acute leukemia (1 paper, 2021). A clonal (malignant) hematopoietic disorder with an acute onset, affecting the bone marrow and the peripheral blood. "The GSTA2 S112T serine homozygosity has been reported to be an independent factor of poor survival in acute leukemia patients who received allogeneic stem cell transplantation." (PMID 34290233, 2021).
adenoma (1 paper, 2019). A neoplasm arising from the epithelium. "In adenoma-normal, we found downregulation of GSTA1 and GSTA2, which encode members of the α class of gluathione-S-transferase enzymes." (PMID 31211760, 2019). "In adenoma-normal, downregulation of DEGs involved in metabolism of brush border proteins (LCT), lipids (APOB/A4), reactive oxygen species (GSTA2), and retinol (RBP2) was observed." (PMID 31211760, 2019).
colitis (1 paper, 2020). Inflammation of the colon. "Analysis of NRF2 target genes involved in ROS detoxification (Nqo1, Gsta2) and heme/iron metabolism (Hmox1) at the apex of acute murine colitis shows a more nuanced picture with all three genes being differentially affected by Nox4 deficiency." (PMID 33059312, 2020).
erythroleukemia (1 paper, 2023). Acute erythroid leukemia characterised by the presence of at least 50% erythroid precursors and at least 20% myeloblasts in the bone marrow. "Additionally, several studies have shown that GSTA2 inhibited the cell death of human erythroleukemia and lens epithelial cells, and these reports indicate that GSTA2 plays a key role in cellular detoxification under oxidative stress." (PMID 36769090, 2023).
gallstones (1 paper, 2024). Solid crystalline precipitates in the biliary tract, usually formed in the gallbladder, resulting in the condition of cholelithiasis. "Furthermore, using RT-qPCR, we observed significant upregulation of AC004692.4, HECW1-IT1, SFRP4, and COMP, while LINC01564, SLC26A3, RP1-27K12.2, and GSTA2 exhibited marked downregulation in gallstone samples." (PMID 38808330, 2024). "The results indicated that AC004692.4, HECW1-IT1, SFRP4, and COMP were significantly higher expressed in gallstone samples, whereas LINC01564, SLC26A3, RP1-27K12.2, and GSTA2 were markedly lower expressed in gallstone samples compared to control samples." (PMID 38808330, 2024).
hepatic cancer (1 paper, 2016). "Herein, the study provides an important evidence where a complex interplay between inflammatory proteins with PXR and its target gene CYP3A11 and GSTa2 are associated with impaired hepatic detoxification in hepatic cancer." (PMID 27760163, 2016). "Such downregulation of PXR, CYP3A11 and GSTa2 and upregulation of drug transporters is expected to have important implications in the treatment regimen of hepatic cancer that could potentially dysregulate hepatic drug biotransformation and bioavailability of administered drugs." (PMID 27760163, 2016). "In the present study, by generating DEN-induced hepatic cancer in mice, we report that the expression of PXR and its target genes CYP3A11 and GSTa2 are down-regulated implying impairment of hepatic detoxification capacity." (PMID 27760163, 2016). "Our results showed significant down-regulation of phase I (e.g. CYP3A11), phase II (e.g. GSTa2) DMEs and upregulation of drug transporters (e.g. MDR1 and MRP3) in hepatic cancer tissues." (PMID 27760163, 2016).
hepatoblastoma (1 paper, 2021). Hepatoblastoma (HB) is a malignant hepatic tumor and is the most common pediatric liver cancer. "The metastatic HCC cell line MHCC97L was found to exhibit the highest expression level of the GSTA2 gene, while the hepatoblastoma cell line HepG2 was detected with the lowest levels of GSTA2 mRNA and protein." (PMID 34290233, 2021).
ischemia (1 paper, 2023). A hypoperfusion of the BLOOD through an organ or tissue caused by a PATHOLOGIC CONSTRICTION or obstruction of its BLOOD VESSELS, or an absence of BLOOD CIRCULATION. "Although oxidative stress is related to ischemic injury, the role of GSTA2 against ischemia has not been elucidated." (PMID 36769090, 2023).
lung carcinoma (1 paper, 2023). "Analysis of 15 GST isoforms of human lung cancer using the TCGA dataset showed GSTP1, GSTA2, GSTA5, GSTO2, and GSTZ1 were significantly upregulated in LUAD compared to corresponding normal tissues, suggesting their potential oncogenic effects on LUAD." (PMID 36709476, 2023).
metastatic colorectal cancer (1 paper, 2022). "High GSTA2 expression predicted poor clinical outcome in metastatic colorectal cancer treated with FOLFOX." (PMID 35433465, 2022).
metastatic tumor (1 paper, 2021). "Importantly, no metastatic tumor was detected in the lung tissue in the GSTA2-suppressing cells, while 3 out of 8 nude mice (37.5%) were found to develop metastatic tumors in the lung in the control group." (PMID 34290233, 2021).
Obesity (1 paper, 2024). Accumulation of substantial excess body fat. "The GSTA2 gene can also play a role in fat deposition and obesity, as this gene is related to oxidative stress, producing an antioxidant enzyme that reduces lipid peroxidation." (PMID 38698200, 2024).
Pneumocystis infection (1 paper, 2010). "Similarly, dexamethasone up-regulated Gsta2 by 4.77 fold, but Pneumocystis infection decreased it by 2.63 fold." (PMID 20377877, 2010).
cancer (11 papers, 2012 to 2026). A tumor composed of atypical neoplastic, often pleomorphic cells that invade other tissues. "The polymorphic feature of GSTA2 is associated with different diseases and cancers." (PMID 34290233, 2021). "At the molecular level, significant upregulation of GPX4 and GSTA2 was observed in both cancer cell lines, whereas NFKB expression increased selectively in HT-29 cells, with no notable changes in CAT or SOD1 expression." (PMID 41745011, 2026). "The results showed that GSTA2 levels were downregulated in the cancer tissues of patients with the PVT1 rs2278176 CT/TT genotype, but not adjacent tissues." (PMID 35433465, 2022). "Moreover, GSTA2 levels were downregulated in the cancer tissues of patients carrying rs2278176 CT/TT genotypes." (PMID 35433465, 2022). "Overexpression of GSTA2 protects cancer cells against apoptosis from chemotherapeutic drugs." (PMID 34290233, 2021). "Moreover, the higher expression levels of certain TSGs, including GSTA2, CCL21, and MADCAM1, were associated with a significantly higher ITR in cancer." (PMID 32774369, 2020). "Both GSTA2 and GSTA1 (which is 28 kb downstream to GSTA2), have been shown to have important roles in catalyzing carcinogenic substrates and nucleotide variation in them has been shown to be associated with cancer." (PMID 25275310, 2014). "Nrf2 mediates multiple antioxidant enzymes, such as glutathione S-transferase A2 (GSTA2) and NADPH quinone oxidoreductase 1 (NQO1), to protect cancer cells from oxidative stress." (PMID 34209775, 2021). "In addition, higher expression levels of GSTA2 were observed in the cancer tissues of patients with SD and PD, but not adjacent tissues." (PMID 35433465, 2022). "Given the importance of ROS generation to the mechanism of mitoKv1.3 inhibitor mediated cell death, it is not surprising to see that cancer cells resistant to PCARBTP upregulated the antioxidant system (GSR, GSTO1, GSTA2, ALDH3A1)." (PMID 35681598, 2022).
tumor (7 papers, 2018 to 2025). "Surprisingly, we also found high expression levels of lipid metabolism genes in the B16F10 tumor cell subpopulation, including Gsta4, Gsta2, Gstp1, and Enpp2." (PMID 38755254, 2024). "We found that the expression level of GSTA2 mRNA was commonly upregulated in HCCs and significantly correlated with tumor size and the presence of venous infiltration." (PMID 34290233, 2021). "The expression of GSTA2 mRNA in tumor or non-tumor tissues was significantly higher than in healthy donors." (PMID 34290233, 2021). "The expression of GSTA2 mRNA in HCC tumor tissues was significantly correlated with the size of the HCC tumor and the presence of venous infiltration." (PMID 34290233, 2021). "In addition, by analyzing the HCC tissues developed from the rat LT model, we found that the expression level of GSTA2 mRNA in the more aggressive tumor tissues was significantly higher than in the less aggressive tumor tissues." (PMID 34290233, 2021). "While downregulated CYP1A1 can reduce the production of ROMs, thus minimizing DNA and protein damage, the upregulation of GSTA2 may allow cytotoxic xenobiotics to accumulate, possibly triggering tumor development." (PMID 30428922, 2018). "SPP1, CRYAB, NNMT and HILPDA were highly expressed in tumour cells (ccRCC1); GSTA2, BHMT and ADSSL1 were highly expressed in tumour cells 1 (ccRCC2); and HIF1A-AS2, DNAH11 and EGOT were highly differentially expressed in tumour cells 2 (ccRCC2)." (PMID 34168986, 2021). "The correlation analysis of the expression of GSTA2 and the identified ROS-associated genes using the LIHC database in the GEPIA web server revealed that the expression level of GSTA2 was significantly correlated with ALB, TPO, APOE, MBL2, and FTH1 in the tumor tissues." (PMID 34290233, 2021). "There was a significant upregulation of GSTA2 mRNA in the tumor tissues compared to the paired non-tumor issues of HCC patients." (PMID 34290233, 2021).
infection (3 papers, 2020 to 2022). The state of being infected such as from the introduction of a foreign agent such as serum, vaccine, antigenic substance or organism. "The gene whose expression was most reduced 72 h after infection was the gene encoding glutathione S-transferase A2 (GSTA2) (−5.58)." (PMID 35746747, 2022). "RSV infection also led to inhibition in mRNA levels of catalase (CAT) and glutathione S-transferase A2 (GSTA2) at later stages of infection which coincide with ROS induction." (PMID 32461278, 2020).
GSTA2 also shares sentences with these, for which no sentence is quoted: breast carcinoma (2 papers); asthma (1); atherosclerosis (1); ciliopathies (1); Cirrhosis (1); colorectal cancer (1); cyst (1); Hepatic steatosis (1); metabolic dysfunction-associated steatotic liver disease (1); pancreatic cancer (1); pulmonary fibrosis (1).